BMP7 (bone morphogenetic protein 7)
Diseases named in the same sentence as BMP7 in open-access papers (continued):
Sharing a sentence is not in itself a finding about the gene and the disease.
tumor (continued). "Other genes were also found to be up-regulated, including Bmp7, which antagonizes transforming growth factor β1 (TGFβ1)-mediated fibrosis through suppressing epithelial-mesenchymal transition, and Mmp8, which prevents metastasis formation through the modulation of tumor cell adhesion and invasion." (PMID 30621584, 2019). "Interestingly, the tumor-promoting effects shown for BMP4 stemmed from mutations in BMP4 or Smads while the tumor-promoting effects of BMP7 did not depended on Smad4." (PMID 28009989, 2017). "In prostate cancer, BMP7 upregulates the expression of NDRG1, a metastasis suppressor gene, which induces senescence in CSCs, leading to tumor dormancy." (PMID 38256140, 2024). "Altogether, these data indicate that tumor-autonomous production of BMP2 and BMP7 synergize to maintain a quiescent-invasive niche in H3.3K27M DIPG." (PMID 39373720, 2024). "Among the tumor suppressor roles of BMPs, they have been reported to induce cancer stem cell differentiation in colorectal CSCs by BMP4 and in GSCs by BMP4 and BMP7." (PMID 38256140, 2024). "BMP7 is also expressed by healthy neural precursor cells from the SVZ and accumulates at the tumor border, leading to a similar paracrine anti-proliferative and pro-differentiating effect." (PMID 38542334, 2024). "-Induces a mismatch in the TGF-β1/BMP-7 pathway of HCC tumour cells, leading to an increase in HCC tumour cells’ stem-like properties and invasive capacity." (PMID 37894344, 2023). "The anticancer effect of PD was demonstrated by the downregulation of tumor suppressor genes via inhibition of the PI3K/Akt signaling and upregulation of bone morphogenetic protein 7 (BMP7)." (PMID 36364001, 2022). "The comparison of differentially expressed genes, specifically in FGFRL1-KD xenografts versus controls, revealed high-ranking upregulated genes such as BMP7 and TIMP3, with specific activities related to tumor–stromal interactions and tumor suppression." (PMID 35053442, 2022). "Consistent with the effects of Meflin on BMP7 signalling and Lox activity, AM80 administration induced a decrease in tumour stiffness and increase in tumour vessel area and intratumoral concentration of GEM." (PMID 35209871, 2022). "The size of the tumor also affected the expression of BMP3 (P = 0.0047), BMP7 (P = 0.0210), BMPR1B (P = 0.0460), ACVR2A (P = 0.0350), ACVRL1 (P = 0.0045), TGFBR2 (P = 0.0170), and TGFBR3 (P = 0.0150) according to the K-W test." (PMID 34036102, 2021). "Nevertheless, our findings support roles for BMP7 in both T cell exclusion and ICB-mediated suppression of MC38 tumor growth." (PMID 32117236, 2020). "In the case of one such CulPRIT, bone morphogenetic protein 7 (BMP7), we demonstrate a functional role in limiting intratumoral CD8+ T cell abundance in murine tumor models." (PMID 32117236, 2020). "BMP7-expressing and control tumors were grown in the mammary fat pad of BALB/c mice and examined for CD8+ T cell infiltration during tumor growth." (PMID 32117236, 2020). "It is noteworthy that activation of the MAPK/ERK and PI3K/Akt pathways is an important step required for EMT process induced by various tumor-related factors including TGF-β, TACC3, EGF, BMP7, ZNF143, and CXCR4 26-31." (PMID 31417642, 2019). "The function of BAMBI in cancer progression, similar to SMAD7 and BMP7, appears to be context dependent; in colorectal malignancies BAMBI is pro-tumorigenic whereas in the lung and bladder cancer BAMBI exhibits anti-tumor properties." (PMID 29799477, 2018). "In the present study, three BMPs members belonging to the Transforming growth factor beta (TGF-β) superfamily, namely BMP3, BMP4 and BMP7, were found hyper-methylated in cDLBCL, supporting the role of BMP families as tumor suppressor genes." (PMID 28912427, 2017). "In melanoma cells, BMP-7 induced MET, a process opposite to EMT at the primary tumor site, thereby leading to metastasis inhibition." (PMID 27661009, 2016).
tumor (continued). "To address this problem, we have recently reported the preparation of a microsphere formulation optimized for loading BMP7, and intended as an intracranial sustained release implant for managing GBM-TICs upon primary tumor resection." (PMID 25860932, 2015). "Since previous studies using GBM-TICs have shown tumor-to-tumor variation in the expression of BMP receptors, we first determined the mRNA levels of BMP7, BMPR1A, BMPR1B and BMPR2 genes by real-time qRT-PCR in our primary cell lines." (PMID 25860932, 2015). "Although all mice died of tumor development, a more pronounced vascularity was seen in untreated and TMZ-treated animals when compared to those treated with BMP7 and combination therapy." (PMID 26546412, 2015). "Two groups of homozygous male mice were used: Group 1 received tumor cells alone in PBS, and group 2 received the same number of tumor cells but were treated with BMP-7 prior to implantation." (PMID 23675191, 2010). "Compact tumor organoids exhibited a higher expression of genes involved in WNT-mediated maintenance of nephron progenitors (e.g. LGR5, MYCN, HMGA2, LIN28B, NCAM, WNT4, BMP7)." (PMID 39740515, 2025). "BMP7, a member of the TGF-β superfamily, primarily functions as a tumor suppressor." (PMID 41395597, 2025). "For example, BMP7 mRNA expression was significantly downregulated in tumor tissues, compared with corresponding non-tumorous tissues." (PMID 37446238, 2023). "Inhibition of metastatic signaling through the downregulation of BMP-7 and MMP-9 expression may interrupt bone–tumor communication." (PMID 34440874, 2021). "Together, these results support the hypothesis that BMP7 expression in tumors may negatively regulate CD8+ T cell infiltration, but with variable phenotypic effects on tumor growth." (PMID 32117236, 2020). "We then performed quantitative real-time PCR (qRT-PCR) analysis for four cell surface receptor genes (PTN, CD24, BMP7, and CADM1), because their protein products are easily detectable by molecular diagnosis and are also related to cell survival, proliferation, or tumor growth." (PMID 33298865, 2020). "We report de‐repression of Bmp2 and Bmp7 in Angptl2−/− ISEMFs and decreased accumulation of β‐catenin in Angptl2−/− mouse crypts, suggesting that ANGPTL2 may function as a tumor promotor in intestine." (PMID 28043948, 2017). "Importantly, a genome-wide gene expression profile established during hepatitis B virus-induced HCC model pointed to BMP7 and BMP4 as candidates for common regulators of genes involved in the non-tumour to tumour-transition." (PMID 29295498, 2017). "Both tumor suppressor genes BMP7 and DAPK1 are downregulated in the absence of MSP in all 3 isoform overexpressing cell lines." (PMID 27323855, 2016). "This lack of general cytotoxicity further indicates that BMP7 therapy does not affect the bulk of the tumor population and thus validates the selectivity of our strategy towards the GBM-TIC subpopulation." (PMID 25860932, 2015). "The data also suggest that BMP7 possesses the ability of anti-EMT/migration/invasion, induction of tumor stem cell differentiation/senescence, and down-regulation of MGMT and drug efflux transporters, thereby allowing for sensitization of GSC to low-dose TMZ treatment." (PMID 26546412, 2015). "However, we cannot preclude additional paracrine factors also contributing to tumor formation since transcripts for other secreted growth regulators (SOST, BMP7, BMP8A, WNT5B, WNT10B, and FGF21) exhibited increased abundance in SHP2-depleted pellet cultures." (PMID 24875294, 2014). "Tumor BMP7 mRNA was not significantly altered by NSAID, compared to sham-treatment (0.57±0.36 vs. 0.40±0.08; p=0.18), respectively." (PMID 25340937, 2014). "In addition, the member genes FGF19, GAS2, BMP7, TNFSF11, and FGFR3 are all known to play important roles in tumor genesis and progression." (PMID 22863767, 2012).
tumor (continued). "The coexpression of molecules such as BMP7, VCAN and EpCAM in EOC cells expressing high CD157 further substantiates this view since these molecules are considered negative prognostic markers involved in the control of the progression of various types of tumor." (PMID 22916288, 2012). "GPC3 modulates the effect of growth factors such as IGF-2, BMP-7 and FGF-2 on hepatoma cells and may recruit M2 tumor-promoting macrophages to the HCC microenvironment." (PMID 22564378, 2012). "The implanted BMP-7 treated G-402 cells not only showed decreased tumor formation at the site of implantation but also developed nodule of ectopic bone containing active bone marrow." (PMID 23675191, 2010). "In summary, the present study showed that BMP-7 inhibited, though not completely, cell proliferation of G-402 and A-549 tumor cells and suppressed tumor formation with ectopic bone formation in a xenograft mouse model." (PMID 23675191, 2010). "BMP7 was homogenously distributed throughout the tumour sections (data not shown)." (PMID 37688374, 2023). "Exogenous BMP7 treatment and augmentation of BMP7 signaling in TMZ-resistant GSCs inhibits self-renewal and migratory capacity, reduces mRNA expression of CD133, MGMT, and ATP-binding cassette drug effluxing transporters and induces senescence, thus sensitizing tumor cells to TMZ treatment." (PMID 34012965, 2021). "Furthermore, BMP4 was capable of inducing tumor dormancy via activating SMAD1/5 signaling and BMP7 can inhibit tumor cell growth and drive CSCs into dormancy by mediating the expression of N-myc downstream-regulated gene 1 and activating p38 MAPK and p21 signaling pathways." (PMID 34712663, 2021). "Although our goal in this study was to study the effect of BMP7 on immune cells in the tumor microenvironment, the downregulation of MAPK14 by BMP7 in resistant tumors cells might also be an important mechanism of resistance to immunotherapies that deserve further investigation." (PMID 32973129, 2020). "In order to determine whether MAPK14 downregulation in TILs depended on BMP7 secretion in the tumor microenvironment, we evaluated the expression of MAPK14 and MAPK14-regulated cytokines and chemokines in TILs isolated from BMP7-knockdown tumors and control tumors treated with IgG or anti-PD1." (PMID 32973129, 2020). "Genetic approaches for elucidation of mechanisms by which BMP7 downregulates MGMT, ABC efflux transporters, stemness, and EMT would further facilitate our understanding the process and ability to identify new treatment targets and strategies for preventing treatment resistance and tumor recurrence." (PMID 26546412, 2015). "Another plausible explanation is that BMP7 induced differentiation at early time points, while the BMP7 dose released from the microspheres was high, but that once the BMP7 concentration decreased below a certain threshold, the remaining GBM-TICs, or dedifferentiated cells, repopulated the tumor." (PMID 25860932, 2015). "Only microspheres with 0.05% w/w of BMP7 presented a statistically significant reduced volume during the whole experiment and at the endpoint, indicating that low BMP7 doses are not sufficient to counteract tumor growth." (PMID 25860932, 2015). "Namely, tumour diameter, nodal involvement, lymphatic invasion and venous invasion were significantly greater in the BMP-7-positive group than in the BMP-7-negative group (P=0.01, <0.01, <0.01 and <0.01, respectively)." (PMID 21224856, 2011). "Furthermore, we confirmed that a top-ranking candidate belonging to the TGF-β superfamily, BMP7, negatively regulates CD8+ T cell abundance in immunocompetent murine tumor models, with and without anti-PD-L1 treatment." (PMID 32117236, 2020). "Indeed, treatment with BMP7 alone allows for delaying tumor development/progression without TMZ compared to untreatment or treatment with TMZ alone, suggesting that the anti-tumor activity of BMP7 is independent of MGMT status in GSC." (PMID 26546412, 2015).
cancer (98 papers, 2008 to 2025). A tumor composed of atypical neoplastic, often pleomorphic cells that invade other tissues. "Several studies have confirmed that decreased expression of BMP6 and BMP7 is associated with fibrosis and cancer cell proliferation." (PMID 39915830, 2025). "BMP7 has been reported in a wide range of human cancers and is associated with metastasis and poor prognosis." (PMID 32973129, 2020). "In BMP7-expressing tumors, Tgfb1 was significantly and simultaneously decreased in myeloid cells (p < 0.001), cancer associated fibroblasts (p < 0.05), and T cells (p < 0.001)." (PMID 32117236, 2020). "BMP7 is essential during development, and more recently has also been implicated in cancer pathogenesis." (PMID 26503415, 2015). "Recently, BMP7 has been implicated in regulation of cancer pathogenesis and metastasis, possibly due to its ability to counteract TGF-β-induced, SMAD3-dependent EMT." (PMID 26546412, 2015). "As well, a significant increase (>20 fold) was observed for BMP7 gene expression, a gene usually associated with cancer progression." (PMID 23721519, 2013). "High expression of pleiotropic signaling molecule BMP7 controls proliferation, migration, and invasion of cancer cells, but this gene might be linked with proliferation, migration, and invasion of pituitary prolactinoma cells." (PMID 33709028, 2021). "Moreover, we observed that amplification of the BMP7 gene locus is significantly associated with reduced CD8+ T cell infiltrates across a range of cancers and is upregulated in immune-privileged organs such as the brain and placenta." (PMID 32117236, 2020). "Moreover, STAT3 (-1.83), EphA2 (-1.74) and BMP7 (-47.17), all proteins involved in signalling pathways associated with cancer stem cell activities, were also found to be down-regulated in the proteomics datasets." (PMID 29568355, 2018). "Using ligand–receptor analysis of reproducible fibroblast clusters, we focused on the cancer cell BMP7–fibroblast ACVR1 axis." (PMID 40745121, 2025). "The correlation between high ACVR1 and BMP7 expression levels and the prognosis of patients with stage II cancer was evaluated." (PMID 40745121, 2025). "BMP-2, commonly overexpressed in diverse cancers and tumor cell lines, predominantly contributes to processes such as in metastasis, EMT and invasion, whereas BMP-7 acts as an inhibitor of metastasis in certain cancers like melanoma." (PMID 38660622, 2024). "There are a limited number of studies, but aberrant expression of BMP7 has been reported in several cancers." (PMID 37688374, 2023). "The tested OS cell lines were characterised by a cancer-related phenotype, such as increased expression of mRNA for BMP-7, as well as MMP-7 and MMP-14." (PMID 36139691, 2022). "BMP7, which has been shown to influence proliferation and cancer cell invasion, exhibited focal expression in our OERCs." (PMID 35205840, 2022). "BMP7 is among the most widely investigated members of the BMP subfamily with respect to cancer, and studies across numerous cancer types have correlated BMP7 with poor prognosis and metastasis." (PMID 36353620, 2022). "The function of BMP7 was to activate a dormant state in cancer cells by p38 MAPK signaling and p21 expression to reduce stemness." (PMID 34745015, 2021). "BMP7, bone morphogenetic protein 7, can regulate immune cell responses and are immunosuppressive in cancer, which can act as a potential immunotherapeutic target." (PMID 33628738, 2020). "In prostate cancer, BMP6 signaling appears to promote cancer progression, while BMP7 induces quiescence in metastatic cancer cells." (PMID 32894216, 2020). "In our study, BMP7 ranked in the top percentile of LFC-ranked tumors in 7 out of 23 cancer types (p = 4.28 × 10−5)." (PMID 32117236, 2020). "It has been reported that bone morphogenetic protein 7 (BMP7) promotes metastatic cancer cell dormancy by activating p38 mitogen-activated protein kinase and increasing p21 expression." (PMID 31753020, 2019).
cancer (continued). "Chronic exposure of cancer cells to BMP7 has been shown to induce the shortening of cancer cell telomeres and subsequent apoptosis." (PMID 29903994, 2018). "CD133+ cell samples also showed higher expression of another cancer stem cell gene, BMP7, compared to CD133−/EpCAM+ cell samples (p = 0.0081)." (PMID 28347289, 2017). "We show that BMP7-induced cancer cell senescence and death are significantly reduced after hTERT gene is constitutively overexpressed to prevent telomerase inhibition." (PMID 27696331, 2017). "To investigate if telomerase inhibition induced by BMP7 mediated BMP7-induced cancer cell senescence, we carried out over- and under-expression of hTERT with GFP-hTERT and GFP-hTERT shRNA gene expression systems respectively, using GFP alone as control." (PMID 27696331, 2017). "We selected 6 genes (MUC4, MUC13, MUC20, BMP7, AKT3, and SMAD3) that were closely associated with the development and progression of cancer to validate the conclusions drawn from the gene expression profiling analysis." (PMID 26673820, 2016). "From in vitro models, including PC12 cells transfected to overexpress BMP7, evidence was provided for non-canoncial signaling through the PI3K/Akt/mTOR pathway leading to overexpression of integrin β1, responsible for the BMP7-induced cancer phenotypes." (PMID 26793165, 2015). "In cancer cells, the TGFB2 and BMP2&4 ligands are implicated with promoting EMT, whereas BMP5 and BMP7 are inhibit basal and/or TGF-β-induced EMT." (PMID 25972361, 2015). "In our series, 11 cases were malignant and nine of them showed high BMP7 expression, suggesting a trend for higher BMP7 levels in malignant tumors." (PMID 26337467, 2015). "BMP7 is a growth factor playing pro- or anti-oncogenic roles in cancer in a cell type-dependent manner." (PMID 26337467, 2015). "Next, to examine the role of Akt activation in cancer migration and integrin up-regulation, we inspected Akt phosphorylation in response to BMP-7 treatment." (PMID 25390068, 2014). "In vitro studies showed that treatment with exogenous BMP-7 markedly increased cellular migration and invasion in breast and prostate cancer cells." (PMID 25390068, 2014). "Previously, in a hepatitis B virus X antigen-induced HCC mouse model, we identified genes that were significantly up-regulated at the pre-cancer and cancer stages, including Edn1, Src, Bmp4, and Bmp7." (PMID 24416389, 2014). "Of these genes, we selected TSPAN8, BST2, BMP7, and Col6A1 for further analysis, because these genes have been reported to be involved in tumorigenicity or cancer cell invasion and migration." (PMID 25221999, 2014). "Of the factors related to metastasis, BMP-7 has been shown to regulate the aggressiveness of cancer cells." (PMID 25390068, 2014). "Recent studies demonstrated that BMP-7 expression is found in various human cancers, and regulates cell differentiation, proliferation, migration, invasion and apoptosis." (PMID 21224856, 2011). "Within PCa it has been shown that BMP7 is significantly underexpressed in laser microdissected cancer cells, leading to an epithelial-to-mesenchymal transition." (PMID 19283074, 2009). "We focused on one of these combinations, BMP7 in cancer cells and ACVR1 in stromal cells." (PMID 40745121, 2025). "Additionally, we investigated cancer cell–fibroblast crosstalk, focusing on the expression of activin receptor type I (ACVR1) in fibroblasts and bone morphogenetic protein 7 (BMP7) in cancer cells as potential therapeutic targets." (PMID 40745121, 2025). "Therefore, we decided to examine the consequence of downregulation of both Bmp7 and Inhba expression in PyMT MECs during cancer progression." (PMID 38708713, 2024).